XPC (XPC complex subunit, DNA damage recognition and repair factor)
Diseases named in the same sentence as XPC in open-access papers (continued):
Sharing a sentence is not in itself a finding about the gene and the disease.
breast carcinoma (continued). "This case-control association study revealed that ERCC1 rs11615 (T allele), XPC rs2228000 (T allele) and ERCC2/XPD rs50872 (T allele) were associated with increased breast cancer risk." (PMID 27768589, 2016). "Our study revealed that XPC rs2228001 was not a risk factor for breast cancer, and this was confirmed by our meta-analysis." (PMID 27768589, 2016). "Likewise, XPC rs2228000 was also significantly associated with the risk of breast cancer in a Chinese population but not Caucasians or African-Americans in the U.S.A.." (PMID 31710080, 2019). "According to alcohol metabolism-involved genes, three were up-regulated (ITGA5, CBS, and SOD2), and six were down-regulated (XDH, XRCC1, MTHFR, CYP1B1, XPC, and GSTP1) among women who died for breast cancer." (PMID 39125744, 2024). "For some genes, single P/LP variants were detected either only in the group of patients with breast cancer (APC, MDM1, MRE11, POLD1, NF1, RAD51C, RECQL4, and WRN) or only in the control group (MCPH1, MSH3, and XPC)." (PMID 39684352, 2024). "Three genes were up-regulated (i.e., ITGA5, CBS, and SOD2), while six were down-regulated (i. e, XDH, XRCC1, MTHFR, CYP1B1, XPC, and GSTP1) among individuals who died of breast cancer." (PMID 32078659, 2020). "For the lymph node involvement subgroup, XPC rs2228001 and ERCC2/XPD rs50872 carriers have a high risk of breast cancer with negative lymph node involvement." (PMID 27768589, 2016). "SRI-011381 alone did not change the expression of XPA, XPB, XPC, and XPF in the breast cancer cells." (PMID 40303493, 2025).
ovarian carcinoma (20 papers, 2011 to 2024). A malignant neoplasm originating from the surface ovarian epithelium. "On the contrary, ERCC1 rs11615 G>A and XPC rs2228000 C>T polymorphisms were associated with significantly reduced risk for ovarian cancer under dominant model." (PMID 29669843, 2018). "Similar results were found in XPC gene, patients carrying rs2228001 CC/AC variant genotype had higher risk of ovarian cancer when compared with those carrying AA variant genotype (adjusted OR = 1.72, 95% CI = 1.02–2.92, P=0.043)." (PMID 29669843, 2018). "Going further, in ovarian cancer, overexpression of the eukaryotic translation initiation factor 3a (eIF3a) was associated with decreased response to cisplatin through downregulating XPC mRNA expression." (PMID 35530314, 2022). "Along with SNPs in two other NER proteins, XRCC1 and XRCC2, the XPC Ala499Val polymorphism was found to correlate to a decreased odds of ovarian cancer (OR 0.35) while the XPC Lys939Gln polymorphism was associated with an increased risk of ovarian cancer (OR 1.72) in a dominant genetic model." (PMID 35530314, 2022). "In addition, the XPC rs2228001 A>C polymorphism has a significant association with an increased risk of ovarian cancer, whereas the variant rs2228000 C>T has the opposite association." (PMID 31572446, 2019). "Therefore, we evaluated the correlation between XPC expression and the prognosis of ovarian cancer by IHC, showing that higher expression of XPC was associated with a poor prognosis." (PMID 31572446, 2019). "The result showed that both ERCC1 rs11615 and XPC rs2228000 were significantly associated with reduced risk of ovarian cancer under dominant genetic model (adjusted OR = 0.35, 95% CI = 0.20–0.61, P=0.0002 and adjusted OR = 0.49, 95% CI = 0.30–0.81, P=0.005 respectively)." (PMID 29669843, 2018). "The wet lab analysis of PRKCG SNP rs1331232028, like many other SNPs in multiple genes, including ERCC1, XPC, PIK3CA, ERBB2 and ERCC2, can be linked to ovarian cancer susceptibility." (PMID 36672978, 2023). "On the other hand, low expression of DMC1 has been reported as a poor prognostic marker of ovarian cancer, together with high expression of XPC and RECQL." (PMID 33202377, 2020). "The results showed that high expression of XPC and RECQL and low expression of DMC1 were associated with poor prognosis in ovarian cancer patients." (PMID 31572446, 2019). "XPC, SMUG1, and GTF2H5 were the top 3 most significant genes associated with ovarian cancer survival according to the prognostic signature." (PMID 31572446, 2019). "Overall, our results suggest that TIE-1 increases NER and DNA repair by up-regulating transcription of XPC, thereby rendering ovarian cancer cells resistant to DNA-adduct-type chemotherapeutic reagents." (PMID 30181600, 2018). "As a result, we found that both variant genotypes of XPC rs2228001 A>C and ERCC2 rs238406 G>T as well as ERCC1 rs3212986 C>A had a significant association with the increased risk of ovarian cancer under dominant and recessive genetic model respectively." (PMID 29669843, 2018). "eIF3a improves ovarian cancer patients' response to DDP-based chemotherapy via down regulating XPC and p27Kip1." (PMID 26213845, 2015). "For instance modulation of XPC by hyperthermia or by treatment with sodium arenite was found to suppress XPC-induced cisplatin toxicity and sensitize tumors to platinum based therapy in a mouse ovarian cancer xenograft model." (PMID 35530314, 2022). "In conclusion, our results indicated that ERCC1, XPC and ERCC2 might influence ovarian cancer susceptibility." (PMID 29669843, 2018). "In conclusion, our study indicated that the ERCC1, XPC and ERCC2 might correlate to ovarian cancer susceptibility." (PMID 29669843, 2018). "However, more comprehensive studies with larger independent cohorts should be performed to unveil the real relationship between these significant genetic variations in the ERCC1, XPC and ERCC2 and ovarian cancer risk." (PMID 29669843, 2018).
ovarian carcinoma (continued). "In the present study, we performed a hypothesis-based association to explore the impact of SNPs in these core genes (XPA, XPC, XPG, ERCC1, ERCC2, and ERCC4) on the risk of ovarian cancer by genotyping a pool of 17 SNPs in 89 patients and 356 controls." (PMID 29669843, 2018). "The current study aims to test the hypothesis that eIF3a may affect the drug response and prognosis of ovarian cancer patients receiving platinum-based chemotherapy by regulating xeroderma pigmentosum complementation group C (XPC) and p27Kip1." (PMID 26213845, 2015). "We also showed that eIF3a may regulate the response of ovarian cancer cells to DDP via down regulating XPC and p27Kip1." (PMID 26213845, 2015). "Moreover, downregulation of XPC could also enhance the sensitivity of ovarian cancer to cisplatin, and XPC SNPs were correlated with survival outcomes of ovarian cancer treated with platinum-based chemotherapy." (PMID 35769257, 2022). "Therefore, we believe that XPC plays a crucial role in the DNA repair pathway of ovarian cancer." (PMID 31572446, 2019). "In addition, XPC rs2228001 and ERCC2 rs238406 had statistically significant association with the increased risk of ovarian cancer under dominant genetic model (adjusted OR = 1.72, 95% CI = 1.02–2.92, P=0.043 and adjusted OR = 2.07, 95% CI = 1.07–4.01, P=0.032 respectively)." (PMID 29669843, 2018). "Therefore, TIE-1 is suggested to promote XPC-dependent NER, rendering ovarian cancer cells resistant to platinum." (PMID 30181600, 2018). "Therefore, we conducted genotyping for 17 SNPs of six NER core genes (XPA, XPC, XPG, ERCC1, ERCC2, and ERCC4) in 89 ovarian cancer cases and 356 cancer-free controls." (PMID 29669843, 2018). "Our thorough evaluation of the NER protein levels (XPA, XPC, XPF, XPG, ERCC1, and DDB2) and corresponding mRNA levels in various cisplatin-sensitive and -resistant ovarian cancer cell lines revealed that the transcript levels of various NER factors do not accurately reflect their protein levels." (PMID 21385444, 2011). "Our in vitro data suggest that inhibition of XPC using siRNA sensitizes ovarian cancer cells to cisplatin (data not shown)." (PMID 21696631, 2011).
melanoma (19 papers, 2014 to 2024). A malignant, usually aggressive tumor composed of atypical, neoplastic melanocytes. "In BRAF-mutant melanomas, loss of p19ARF promotes the epigenetic silencing of XPC, leading to deficiencies in nucleotide excision repair." (PMID 34210801, 2021). "This is well known for XPC mutations that are associated with high rate of basal cell carcinomas (BCCs), squamous cell carcinomas (SCCs), and melanoma in photo-exposed skin." (PMID 33329698, 2020). "It occurs as a haplotype with a second polymorphism in the XPC gene that is associated with an increased risk for skin cancer development, SCCs and melanoma." (PMID 29416673, 2018). "They found that XPC rs2228000 CT and TT genotypes were significantly associated with decreased melanoma risk when compared with the reference genotype." (PMID 27847809, 2016). "Reduced XPC was also found associated with earlier onset of disease and poorer survival in a cohort of predominantly high sun exposed melanomas." (PMID 27487145, 2016). "XPC is a DNA damage recognition protein, therefore deficiency is likely to play a key role in the accumulation of mutations in melanoma, and possibly development of treatment resistance and disease progression." (PMID 27487145, 2016). "Some XPC gene SNPs have been identified to be implicated in melanoma, colorectal cancer, prostate cancer, hepatocellular cancer, lung cancer, and gastric cancer." (PMID 27847809, 2016). "Therefore, loss of GGR, in particular XPC, in melanoma could play a role in resistance to platinum chemotherapies." (PMID 29373959, 2018). "Subdividing the whole TCGA-SKCM cohort by median age, we found that in melanoma tissue from younger patients, XP cluster 1 genes and also XPC and DDB2, belonging to XP cluster 2, were expressed to a relatively higher extent." (PMID 35174087, 2022). "The majority of melanoma cell lines showed an induction of XPC (range = 1.1–3.2 fold increase) and increased apoptotic cell death after the decitabine/carboplatin sequential treatment compared to carboplatin alone (range = 1.6–2.2 fold increase)." (PMID 32569203, 2020). "Performing germline/tumour whole-exome sequencing of 44 stage III/IV melanoma patients we identified pathogenic germline mutations in CDKN2A, CDK4, ATM, POLH, MRE11A, RECQL4 and XPC, affecting 7/44 patients." (PMID 33077847, 2020). "A region -3000 bp upstream of XPC was fully methylated (β > 0.6) in 125 melanomas (33.1%) and partially methylated (β 0.2–0.6) in 253 melanomas (66.9%)." (PMID 32569203, 2020). "Carboplatin alone resulted in small increases in XPC expression in three melanoma cell lines (MM200, Me4405 and Mel-RM)." (PMID 29373959, 2018). "Here our data indicate that, in melanocytes and melanoma, DOT1L and H3K79 methylation is required for XPC recruitment and efficient NER, and loss of DOT1L leads to UV sensitivity and inefficient removal of UV photoproducts." (PMID 29343685, 2018). "Melanoma cell lines were treated with decitabine (0.26 μM) and carboplatin (8 μg/mL), both individually and in sequential combination and the expression of XPC was measured." (PMID 29373959, 2018). "Decitabine followed by DNA-damaging carboplatin treatment led to significantly higher XPC expression in 75% of melanoma cell lines tested." (PMID 29373959, 2018). "A mouse model found that melanocytes with BRAFV600E and p14ARF−/− background developed melanoma in response to UV radiation, with impaired DNA repair capacity due to reduced XPC expression from promoter hypermethylation." (PMID 29373959, 2018). "Taken together, this data shows that global demethylation with decitabine does occur and can increase XPC mRNA expression in melanoma." (PMID 29373959, 2018). "We also identified that melanoma tumours with low XPC expression have significantly shorter survival." (PMID 29373959, 2018). "Overall these results suggest that the effects of combination treatment are at least partially dependent on the increased XPC expression in melanoma cells." (PMID 29373959, 2018).
melanoma (continued). "The most comprehensive was the TCGA data which showed a trend towards confirming the relationship between low XPC and poorer survival, but this requires confirmation in a large cohort of melanomas using a quantitative measure of XPC." (PMID 27487145, 2016). "Transcriptome analysis was used to investigate biological processes that differed between the XPC- and XPC+ melanomas." (PMID 27487145, 2016). "The attenuation of post-UVB XPC expression was confirmed at the protein level in all melanoma cell lines, except Mel-RM." (PMID 27487145, 2016). "Transcriptome analysis of melanomas with low XPC revealed increased expression of transcripts involved in other DNA repair processes, in particular double strand break repair (DSBR)." (PMID 27487145, 2016). "The high XPC expressing melanomas displayed significantly higher expression of immune response related transcripts." (PMID 27487145, 2016). "An XPC−/−Ink4a-Arf−/− double knockout mouse model developed significantly more melanomas after a single neonatal dose of UVB than Wildtype or single knockout mice and XPC expression was lost in up to 59% of SCCs via chromosome 3p loss or XPC mutation." (PMID 27487145, 2016). "In the melanoma tumours, XPC expression correlated with age of diagnosis and low XPC conferred significantly poorer survival." (PMID 27487145, 2016). "The XPC expression in melanoma also reflected the CPD repair occurring predominantly after 24 h in all melanoma cell lines." (PMID 26913219, 2015). "A notable difference between melanoma cell lines and melanocytes was observed for XPC protein expression." (PMID 26913219, 2015). "In comparison, melanoma cells displayed a delayed response, with transcript expression peaking at 24 or 48 h and XPC protein peaking at 24 h in all cell lines except Me4405." (PMID 26913219, 2015). "XPC transcript expression was significantly higher in melanocytes compared to all melanoma cell lines at 4 h." (PMID 26913219, 2015). "Similarly, different genetic variations within XPC and XPD were associated with melanoma susceptibility, while one mutation appeared as a protective factor against melanoma." (PMID 38686623, 2024). "As demethylation increased XPC mRNA expression in melanoma, the promoter region of XPC, containing the CpG island and adjacent shores, was bisulfite sequenced in all melanoma cell lines before and after decitabine treatment to identify if promoter methylation is responsible for reduced expression." (PMID 29373959, 2018). "However, at this dose only two of the four melanoma cell lines had a significant increase in XPC mRNA expression (1.23-2.99 fold) (Me4405 p = 0.0003, Mel-RM p < 0.0001), which was lower than the increase seen with 10 μM." (PMID 29373959, 2018). "The key GGR component XPC does not respond to DNA damage in melanoma, the cause of this lack of response has not been investigated." (PMID 29373959, 2018). "In this study, we investigated the effect of DNA methylation on the expression of XPC in melanoma." (PMID 29373959, 2018). "In this study, we investigated the role of methylation in reduced XPC in melanoma." (PMID 29373959, 2018). "To date, somatic mutations in XPC, DDB1 and DDB2 have rarely been reported in melanoma tumours." (PMID 29373959, 2018). "The poor S-phase repair observed in melanoma in this study may indeed be a consequence of reduced or delayed apoptosis as a result of reduced XPC, but to confirm this further studies are required." (PMID 27487145, 2016). "In addition, melanomas expressing lower than the mean XPC (XPC-) had 164.14 (95% CI 115.82 - 212.46) median weeks survival compared to 547.29 (95% CI 142.12 - 952.45) median weeks survival for those with high XPC expression (XPC+) (χ2 = 4.34 p = 0.037)." (PMID 27487145, 2016). "XPC transcript displayed a bimodal induction pattern, with expression peaking at 4 and 48 h and was significantly higher in melanocytes compared to all melanoma cell lines, at 4 h following UVA exposure." (PMID 26913219, 2015).